MAL (mal, T cell differentiation protein (MAL blood group))
Diseases named in the same sentence as MAL in open-access papers (continued):
Sharing a sentence is not in itself a finding about the gene and the disease.
breast carcinoma (7 papers, 2009 to 2023). "An example of MAL-family proteins affecting raft condensation is that of MAL in breast cancer cells, in which MAL levels affected the protein composition of membrane rafts, with consequences for cell motility." (PMID 37345137, 2023). "A high frequency of RASSF1A (83.3%) and MAL (41.7%) methylation was identified in the breast carcinomas." (PMID 19778456, 2009). "The expression of MAL is significantly down-regulated, and it plays an important role as a binding gene of MUC1 in breast cancer." (PMID 36059531, 2022). "The scrutiny of the two sources of information, datasets and published studies, reveals potential prognostic applications of MAL-family members as cancer biomarkers—for instance, MAL2 in breast cancer, MAL2 and MALL in pancreatic cancer, and MAL and MYADM in lung cancer—and other biomedical uses." (PMID 37345137, 2023). "Methylation-sensitive high-resolution melting was used to screen promoter methylation in a panel of 13 genes reported as methylated in breast cancer (RASSF1A, TWIST1, APC, WIF1, MGMT, MAL, CDH13, RARβ, BRCA1, CDH1, CDKN2A, TP73, and GSTP1) in 29 tumour pairs (16 ipsilateral and 13 contralateral)." (PMID 26452468, 2015).
esophageal cancer (7 papers, 2008 to 2021). A primary or metastatic malignant neoplasm involving the esophagus. "A previous study in mouse esophageal carcinoma showed that loss of MAL expression is correlated to tumor progression, and ectopic expression of MAL prevents tumor formation by triggering apoptosis of tumor cells." (PMID 23349797, 2013). "In other gastrointestinal cancers, that is, colorectal and oesophageal cancer, the T-lymphocyte maturation associated protein MAL, involved in glycolipid-enriched membrane-mediated apical transport, has been described to be inactivated by promoter hypermethylation." (PMID 19002170, 2008). "The reactivated expression of MAL gene exerts an inhibitory effect on motility and tumorigenicity of esophageal cancer." (PMID 21092172, 2010). "Hypermethylation of the MAL promoter has been shown in colorectal and oesophageal cancers and MAL has been proposed as a putative tumour suppressor in these cancer types." (PMID 19002170, 2008). "T-lymphocyte maturation associated protein, MAL, has been described as a tumour-suppressor gene with diagnostic value in colorectal and oesophageal cancers, and can be inactivated by promoter hypermethylation." (PMID 19002170, 2008). "In addition, the decreased expression of DSG3, SPRR3 and MAL, which were all also decreased under conditions of ATRA absence in our experiment, were reported to be related to a poor prognosis of esophageal cancer." (PMID 32556644, 2020). "Previous reports have showed the absence of the T cell differentiation protein, MAL, in clear cell carcinoma as well as esophageal carcinoma although it was highly expressed in normal tissue." (PMID 26992238, 2016). "Accordingly, our results also demonstrated that exogenous expression of MAL could suppress the invasive ability and tumorigenicity of HNSCC cells, which was consistent with the findings described in esophageal cancer." (PMID 21092172, 2010).
serous ovarian cancer (6 papers, 2015 to 2021). "The gene encoding for myelin and lymphocyte protein (MAL) has been reported to be among the most highly expressed genes in serous ovarian cancers from short-term survivors (< 3 years) compared with those of long-term survivors (> 7 years)." (PMID 35582723, 2019). "Overexpression of the MAL gene was used to predict chemoresistance and poor prognosis in serous ovarian cancer patients." (PMID 34109184, 2021). "MAL was largely unmethylated at the transcriptional start site in serous ovarian cancers." (PMID 35582723, 2019).
bladder cancer (5 papers, 2020 to 2024). "This validation study confirmed the diagnostic performance of the methylation marker panel GHSR/MAL for detecting bladder cancer among patients with hematuria using urine samples collected at home." (PMID 39412544, 2024). "Taken together, testing for the methylation marker panel GHSR/MAL in urine may provide a valuable non-invasive strategy to detect bladder cancer." (PMID 35123558, 2022). "For MAL, “B cell receptor signaling pathway”, “bladder cancer”, “cell cycle”, “chronic myeloid leukemia”, “glycine serine and threonine metabolism”, “leukocyte transendothelial migration”, “pancreatic cancer”, “small cell lung cancer” were enriched in eight gene sets (n = 552) (FDR < 0.05)." (PMID 32099532, 2020). "All nine urinary methylation markers (FAM19A4, GHSR, MAL, miR-129, miR-935, PHACTR3, PRDM14, SST and ZIC1) showed significantly higher methylation levels in bladder cancer patients than in controls (p < 0.001)." (PMID 35123558, 2022). "The urinary methylation levels of FAM19A4, GHSR, MAL, miR-129, miR-935, PHACTR3, PRDM14, SST and ZIC1 were significantly higher in patients with bladder cancer than in controls (all, p < 0.001)." (PMID 35123558, 2022). "In our prior preclinical study addressing technical aspects and involving 100 bladder cancer patients and 108 controls with and without hematuria, we identified hypermethylation of GHSR/MAL as urinary biomarkers with good diagnostic potential." (PMID 39412544, 2024). "In contrast, MAL promoter hypermethylation and concomitant MAL downregulation have been described in other epithelial malignancies, such as colon, breast, salivary gland cancers, non-small cell lung cancer (NSCLC) and bladder cancer." (PMID 35093120, 2022). "These encompass seven protein-coding genes (FAM19A4, GHSR, MAL, PHACTR3, PRDM14, SST and ZIC1)—of which, the CpG islands are methylated in bladder cancer—as well as two miRNAs (miR-129 and miR-935) with promoter regions that are also known to be methylated in bladder cancer." (PMID 32252299, 2020).
cervical disease (5 papers, 2016 to 2025). "Methylation of CADM1, MAL, and miR124 has been related to the severity and duration of cervical disease." (PMID 31067838, 2019). "In this study, we explored CADM1, MAL and miR124-2 DNA methylation using clinician-collected and self-collected HPV+samples from Papua New Guinea, a setting with a high burden of cervical disease." (PMID 38904134, 2024). "Host DNA methylation markers CADM1, MAL and miR124 have been identified in cervical disease, but not anal disease." (PMID 35241698, 2022).
COVID-19 (5 papers, 2021 to 2024). A disease caused by infection with severe acute respiratory syndrome coronavirus 2. "Taken together, we found that COVID-19 severity in the Ghanaian cohort was associated with dysregulated inflammatory response mediated by MAL, IL1A, IL23A, CRNN, and S100A7 overexpression and suppression of antiviral immune response-related pathways." (PMID 38375062, 2024). "MAL protein expression was augmented in lipid-raft-associated sucrose density gradient fractions after treating human SAECs with pEVs from COVID-19 patients compared to non-COVID-19 patients." (PMID 36675169, 2023). "In summary, the Bayesian network analysis highlighted that specific signaling pathways, including interleukin signaling, MyD88:MAL signaling, TLR signaling, and innate immune response, are associated with the AUC in severe COVID-19." (PMID 37918965, 2024). "The MAL gene, an essential component in NF-κB pathway activation, and serine protease TMPRSS11B were among the top overexpressed genes in our severe COVID-19 cohort (Supplementary 4)." (PMID 38375062, 2024). "We found the upregulation of TLE1, MAL and ZBTB16 in the tears of COVID-19 patients." (PMID 34615949, 2021). "In addition, the MAL gene, an important component in NF-κB signaling pathway activation, and TMPRSS11B were among the top 10 upregulated genes in Ghanaians with severe COVID-19." (PMID 38375062, 2024). "Secondly, we showed that the density of the lipid raft protein MAL (and potentially MAL2) is augmented in light-density sucrose gradient fractions from human SAECs challenged with pEVs from COVID-19 patients compared to those from non-COVID-19 patients." (PMID 36675169, 2023).
head and neck squamous cell carcinoma (5 papers, 2010 to 2022). A squamous cell carcinoma that arises from any of the following anatomic sites: lip and oral cavity, nasal cavity, paranasal sinuses, pharynx, larynx, and salivary glands. "The tumour suppressive properties of MAL have been verified in head and neck squamous cell carcinoma where the decrease of expression is associated with tumorigenesis, and the exogenous expression of MAL decreased cell proliferation and increased apoptosis." (PMID 26056366, 2015). "To identify new and useful candidate biomarkers in head and neck squamous cell carcinoma (HNSCC), we performed a genome-wide survey and found that Myelin and lymphocyte-associated protein (MAL) was a gene that was markedly down-regulated in HNSCC." (PMID 21092172, 2010). "In head and neck squamous cell carcinoma, MAL expression was downregulated, and its overexpression reduced cell proliferation, cell cycle progression, and invasion and increased apoptosis." (PMID 26992238, 2016).
Hodgkins lymphoma (5 papers, 2008 to 2023). A heterogeneous group of malignant lymphoid neoplasms of B-cell origin characterized histologically by the presence of Hodgkin and Reed-Sternberg (HRS) cells in the vast majority of cases. "Interestingly, MAL overexpression in cutaneous T-cell lymphoma was associated with resistance to alpha-interferon therapy, and its expression was indicative of poor prognosis in Hodgkin’s lymphoma." (PMID 28545541, 2017). "It is of note that, as revealed by immunostaining, about 19% of classic Hodgkin lymphomas expressed MAL, and its expression correlated with nodular sclerosis subtype." (PMID 33946345, 2021). "Interestingly, also in Hodgkin's lymphoma patients a similar association was found with a significantly worse survival in patients whose tumours expressed the MAL protein compared with patients with tumours lacking MAL expression, indicating a prognostic value of MAL also in other cancer models." (PMID 19002170, 2008). "Interestingly, MAL is highly expressed in mediastinal large B cell lymphoma and a subset of Hodgkin lymphoma with poor prognosis." (PMID 37505692, 2023). "Therefore, MAL expression provides additional evidence of a link between classic Hodgkin lymphoma and primary mediastinal lymphoma." (PMID 33946345, 2021). "Specifically, over one-third of all PMLBCL signature genes, including MAL, SNFT, TNFRSF6, TARC, and CD30, were found to be highly expressed in the Hodgkin lymphoma." (PMID 23198190, 2012).
malaria (5 papers, 2011 to 2021). Malaria is a serious and sometimes fatal disease caused by a parasite that commonly infects a certain type of mosquito which feeds on humans. "Heterozygosity for the MAL/TIRAP variant in the TLRs pathway have been suggested to provide protection against invasive pneumococcal disease, malaria, tuberculosis and chagas disease." (PMID 33868225, 2021). "The study compared antibody levels to Plasmodium merozoite antigens (MSP1, MSP2 MSP3, EBA17) between four groups of children, defined according to infection with malaria and/or intestinal parasites (MAL-IP-, MAL+IP-, MAL+IP+, MAL-IP+)." (PMID 33170876, 2020). "The current immunogenetic study was designed to analyse the key components of innate immunity, TLRs and TIRAP (Toll-interleukin-1 receptor domain-containing adaptor protein), also known as MAL (MYD88 adaptor-like), in Iranian patients with mild malaria." (PMID 21457584, 2011). "Among the children, 76.3% were slide-positive for malaria (MAL+), with 59.4% having malaria without intestinal parasites (MAL+, IP-) and 16.9% being coinfected with malaria and intestinal parasites (MAL+, IP+)." (PMID 33170876, 2020). "Thus, it was important to take age into consideration when making comparison between children infected with malaria (MAL+,IP-), co-infected with malaria and IP (MAL+,IP+) and those who were not infected (MAL-,IP-) at the time the study was conducted." (PMID 33170876, 2020).
B-cell lymphoma (4 papers, 2020 to 2024). "MAL expression in B-cell lymphomas has been investigated in both Hodgkin and non-Hodgkin lymphomas." (PMID 33946345, 2021). "Mature B-cell lymphoma included DLBCL (38 cases, 51.4%), FL (7 cases, 9.5%), MCL (4 cases, 5.4%), MAL T (2 cases, 2.7%), and BL (1 case, 1.4%)." (PMID 38604163, 2024).
adenoma (3 papers, 2008 to 2015). A neoplasm arising from the epithelium. "A set of transcripts (18 genes including MAL, SFRP1, SULT1A1, PRIMA1, PTGDR) showed decreasing expression (p < 0.01) in the biopsy samples along the adenoma-carcinoma sequence." (PMID 26482433, 2015). "Within 60 adenoma samples (median age 67 years) successfully amplified by qMSP, promoter hypermethylation was detected in 90%, 68%, 42%, 85% and 55% for CNRIP1, FBN1, INA, MAL, and SNCA, respectively, and 90% of the adenomas harbored co-methylation." (PMID 21777459, 2011). "ADAMTS1, CDKN2A, CRABP1, MLH1, NR3C1, RUNX3, and SCGB3A1 showed increasing methylation frequencies from adenomas to carcinomas, while HOXA9, MAL, and MGMT displayed overall equal methylation frequencies in all tumor subgroups." (PMID 19117505, 2008). "No significant gene expression alterations could be detected in the stromal cells isolated from adenomas compared to the normals, but COL1A2, FADS1, MAL, PRIMA1, SULF1, THBS2, TIMP1 genes’ transcripts showed significant differences (p < 0.05) in logFc values for the tumour versus normal comparison." (PMID 26482433, 2015). "miR-21 was found to be significantly (p < 0.01) upregulated in adenoma and tumour samples compared to the healthy colonic tissue controls and could explain the altered expression of genes for which DNA methylation changes do not appear to play role (e.g. BCL2, MAL, PTGS2)." (PMID 26482433, 2015).
cervical intraepithelial neoplasia (3 papers, 2022 to 2024). "CADM1 methylation was detected in 38 (73.1%) and MAL methylation in 25 (48.1%) across all cervical dysplasia patients." (PMID 36010947, 2022). "The methylation of CpG sites for both CADM1 and MAL have previously been indicated as potential biomarkers in HPV-related cervical intraepithelial neoplasia (CIN) with reports of 78% specificity and 70% sensitivity in women with HRHPV infections for histological CIN3+30." (PMID 35241698, 2022).
Chagas disease (3 papers, 2018 to 2021). A parasitic infection caused by Trypanosoma cruzi. "During Trypanosoma cruzi infection, the causative agent of Chagas disease, it was shown in a mouse model of infection that MAL deficiency is associated to exacerbated inflammation, similarly to TLR-2 deficient mice, leading to decreased parasitemia and delayed mortality." (PMID 33072109, 2020).
depression (3 papers, 2023 to 2025). "The selective upregulation of MOG and MAL in response to Ω3D intervention, as observed in our study, is particularly noteworthy given their potential roles in the context of depression." (PMID 39492773, 2025). "Decreased levels of MAG, MAL, CNPase, and MOBP, were also confirmed in animal models of depression and in the human postmortem study in depressed patients." (PMID 38235150, 2023).
lung adenocarcinoma (3 papers, 2021 to 2026). A carcinoma that arises from the lung and is characterized by the presence of malignant glandular epithelial cells. "We demonstrated here that high-MAL gene expression seems to confer survival advantages for patients with melanoma, lung adenocarcinoma, pancreatic adenocarcinoma, renal cancer, or colorectal adenocarcinoma." (PMID 33672337, 2021). "The purpose of this work was to investigate whether ectopic expression of MAL could modify the proliferative activity of MUC1 in human lung adenocarcinoma HCC827 cells." (PMID 42038033, 2026). "Notably, we demonstrated that both high-MAL gene expression and low-VILL gene expression seem to synergistically confer survival advantages for patients with melanoma, lung adenocarcinoma, pancreatic adenocarcinoma, or renal cancer." (PMID 33672337, 2021).
prostate carcinoma (3 papers, 2014 to 2025). A carcinoma that arises from epithelial cells of the prostate gland. "Our findings support the original hypothesis that methylation status of six selected index genes (HSPB1, CCND2, TIG1, DPYS, PITX2, and MAL) provides a novel, objective, and accurate prediction of death from prostate cancer in men clinically assessed as low to intermediate risk." (PMID 27708246, 2016). "In a recent report, we demonstrated that changes in methylation of HSPB1, CCND2, TIG1, DPYS, and, MAL, had significant prognostic effects in multivariate Cox models where death from prostate cancer was the study endpoint." (PMID 27708246, 2016). "Methylation was quantified by pyrosequencing assays for six genes (HSPB1, CCND2, TIG1, DPYS, PITX2, and MAL) with established biomarker value in prostate cancer." (PMID 27708246, 2016). "Assays measuring methylation of MAL, TIG1, HSPB1, CCND2, and DPYS have potential to accurately stratify early prostate cancers and thereafter to manage affected patients in a biologically appropriate manner." (PMID 25193387, 2014). "A model including PSA, and methylation of DPYS, HSPB1, MAL and TIG1 was better at predicting prostate cancer-related mortality than a model based only on gene methylation." (PMID 25193387, 2014). "Thus, based on our results, WFA‐ and MAL I ‐reactive PSA‐glycoforms are not optimal markers for prostate cancer detection, although direct comparison of tissue and serum glycoforms may be hampered, e.g., by the presence of glycosidases in blood circulation." (PMID 40635354, 2025).
schizophrenia (3 papers, 2017 to 2023). A major psychotic disorder characterized by abnormalities in the perception or expression of reality. "Genes enriched in myelin-forming oligodendrocytes were also transcriptionally downregulated in the PFC in schizophrenia subjects: myelin and lymphocyte protein (MAL), 2′,3′-cyclic nuclei 3′-phosphodiestarase, myelin-associated protein (MAG), transferrin, gelsolin, HER3 (ErbB3)." (PMID 36833173, 2023). "There are consistent reports of reduced expression of genes (MAG, MAL, MBP, PLP, MOG, NRG1, and Olig2, among others) associated with oligodendrocytes and myelin, and therefore involved in neuronal development or signal transmission in schizophrenia." (PMID 35326310, 2022). "Several of the upregulated genes (e.g. MAG, MAL and CNP) have previously been reported as downregulated in post-mortem brain samples from schizophrenia patients." (PMID 29187753, 2017).
Sepsis (3 papers, 2011 to 2023). Sepsis is defined as life-threatening organ dysfunction caused by a dysregulated host response to infection. "The DE miRNAs (miR-1246, miR-200, miR-223, miR-29b, and miR-145) reported earlier in sepsis patients, for example, contribute to regulation of signaling molecules (IKKα, MAL, TRAF6, MyD88) in the TLR-4 pathway during LPS exposure." (PMID 33113825, 2020). "In C4_RPL34 cells in the context of S. viridans sepsis, genes co-expressed with CTSD were related to “Leukocyte migration,” “Intrinsic apoptotic regulation,” and “MYD88: MAL cascade initiation,” which may contribute to disease pathogenesis." (PMID 37919720, 2023).